ENSG00000269825 (novel zinc finger protein)
Synonyms: LOC122539214
Gene: Protein-coding gene on chromosome 19 (52,594,060 to 52,690,559, reverse strand). Ensembl gene ENSG00000269825.
Gene Ontology:
Molecular function: DNA-binding transcription activator activity, RNA polymerase II-specific; RNA polymerase II cis-regulatory region sequence-specific DNA binding; sequence-specific DNA binding
Biological process: regulation of transcription by RNA polymerase II; negative regulation of DNA-templated transcription; positive regulation of transcription by RNA polymerase II; regulation of DNA-templated transcription
Cellular component: nucleus
Genetic constraint (gnomAD): Missense variants: 164 observed, 193.05 expected, observed/expected ratio (o/e) 0.85, 90% interval 0.75 to 0.97. Synonymous variants: 50 observed, 59.95 expected, observed/expected ratio (o/e) 0.83, 90% interval 0.66 to 1.06.
Homologues: Paralogues in human: ZNF816 (69% identical), ZNF888 (68% identical), ZNF813 (67% identical), ZNF860 (66% identical), ZNF761 (64% identical), ZNF578 (62% identical), ZNF468 (56% identical), ZNF765 (55% identical), ZNF701 (52% identical), ZNF525 (52% identical), ZNF766 (39% identical).